WNT1 (Wnt family member 1)
Description:
Ligand for members of the frizzled family of seven transmembrane receptors (Probable). Acts in the canonical Wnt signaling pathway by promoting beta-catenin-dependent transcriptional activation. In some developmental processes, is also a ligand for the coreceptor RYK, thus triggering Wnt signaling (By similarity). Plays an essential role in the development of the embryonic brain and central nervous system (CNS) (By similarity). Has a role in osteoblast function, bone development and bone homeostasis.
Synonyms: INT1; BMND16; OI15
Tractability: Antibody: UniProt places it where antibodies can reach, with high confidence; its Gene Ontology location is reachable by antibodies, with high confidence; UniProt predicts a signal peptide or a membrane-spanning region.
Gene: Protein-coding gene on chromosome 12 (48,978,322 to 48,982,620, forward strand). Ensembl gene ENSG00000125084.
Subcellular location: Secreted, extracellular space, extracellular matrix; Secreted
Pathways (Reactome):
Signal Transduction: Class B/2 (Secretin family receptors); Disassembly of the destruction complex and recruitment of AXIN to the membrane; PCP/CE pathway; TCF dependent signaling in response to WNT; WNT ligand biogenesis and trafficking
Developmental Biology: Transcriptional regulation of white adipocyte differentiation
Gene Ontology:
Molecular function: cytokine activity; receptor ligand activity; frizzled binding; morphogen activity; protein domain specific binding; signaling receptor binding
Biological process: bone development; canonical Wnt signaling pathway; negative regulation of apoptotic process; negative regulation of BMP signaling pathway; negative regulation of cell-cell adhesion; negative regulation of cell-substrate adhesion; negative regulation of cellular senescence; positive regulation of cell population proliferation; positive regulation of dermatome development; positive regulation of DNA-templated transcription; positive regulation of fibroblast proliferation; positive regulation of insulin-like growth factor receptor signaling pathway; positive regulation of lamellipodium assembly; positive regulation of Notch signaling pathway; response to wounding; signal transduction in response to DNA damage; cell fate commitment; cell-cell signaling; central nervous system morphogenesis; cerebellum formation; embryonic axis specification; midbrain development; midbrain dopaminergic neuron differentiation; negative regulation of fat cell differentiation; neuron differentiation; and 10 more
Cellular component: cytoplasm; extracellular region; endocytic vesicle membrane; endoplasmic reticulum lumen; extracellular exosome; Golgi lumen; plasma membrane; cell surface
Genetic constraint (gnomAD): Loss-of-function variants: 13 observed, 21.6 expected, observed/expected ratio (o/e) 0.6, 90% interval 0.39 to 0.96. The upper end of that interval is the gene's LOEUF score, 0.96, which puts it in group 4 of 6, group 1 being the genes least tolerant of losing a copy. Missense variants: 475 observed, 495.51 expected, observed/expected ratio (o/e) 0.96, 90% interval 0.89 to 1.03. Synonymous variants: 208 observed, 213.75 expected, observed/expected ratio (o/e) 0.97, 90% interval 0.87 to 1.09.
Homologues: Orthologues: chimpanzee WNT1 (100% identical), macaque WNT1 (99% identical), pig WNT1 (99% identical), dog WNT1 (99% identical), mouse Wnt1 (99% identical), rabbit WNT1 (99% identical), rat Wnt1 (99% identical), guinea pig WNT1 (93% identical), zebrafish wnt1 (76% identical), tropical clawed frog wnt1 (71% identical), Drosophila melanogaster wg (56% identical), Caenorhabditis elegans cwn-1 (36% identical). Paralogues in human: WNT4 (44% identical), WNT3 (43% identical), WNT6 (43% identical), WNT3A (43% identical), WNT2B (40% identical), WNT2 (39% identical), WNT10A (39% identical), WNT5A (39% identical), WNT10B (37% identical), WNT16 (37% identical), WNT5B (37% identical), WNT7A (36% identical), and 6 more.
Diseases named in the same sentence as WNT1 in open-access papers:
WNT1 is named in the same sentence as 231 diseases in open-access papers, as found by Europe PMC text mining. Sharing a sentence is not in itself a finding about the gene and the disease. The quoted sentences say what the papers report.
breast cancer (251 papers, 2003 to 2026). A primary or metastatic malignant neoplasm involving the breast. "We previously evaluated the role of Lrp5 and Lrp6 in a mammary tumor model in which the ectopic expression of Wnt1 under the control of the MMTV promoter (MMTV-Wnt1) causes the rapid onset of mammary tumors." (PMID 40932232, 2025). "To further understand the influence of the microbiota on tumor development stemming from genetic predisposition, we also tested Wnt1-transgenic mice, a model for mammary carcinoma development." (PMID 39969175, 2025). "We have also found that Wnt1 deregulation is associated with survival outcome in patients with gastric and breast cancer." (PMID 36056132, 2022). "In case of breast cancer, high expression of Wnt1 was associated with less number of patients at risk." (PMID 36056132, 2022). "To quantitively determine how obesity is linked to increased risk of breast cancer, we orthotopically implanted E0771 and TeLi (Wnt1-driven) cells at limiting dilutions in a C57BL/6J diet-induced obesity model and measured tumor formation." (PMID 35013251, 2022). "With respect to laboratory mice, it has been demonstrated that the integration of MMTV proviral DNA into the mouse genome near one or more of the protooncogenes, such as Wnt-1 and Fgf, is associated with the development of mouse mammary tumours." (PMID 35458452, 2022). "In case of breast cancer patients, Kaplan‐Meier curve and log‐rank test analyses showed that high expression of Wnt1 (HR = 0.83; P = 0.0004) was associated with less number of patients at risk." (PMID 36056132, 2022). "Wnt1 mutations were found in different types of cancers like adenomatous polyposis coli, colorectal cancer, and lung cancer, breast cancer, gastric cancer." (PMID 36056132, 2022). "NANOG induction in association with WNT1 pathway induces tumorigenesis in murine mammary gland and enhances mammary tumour metastasis." (PMID 34203746, 2021). "To study the mechanistic relevance of these associations in vivo, we knocked out FAK and disrupted its kinase function through a knock-in mutation, in the Wnt1-induced basal-like breast cancer mice model." (PMID 32493400, 2020). "Expression of miRNA-140-5p is frequently down regulated in breast cancer stem cells and its inhibitory effects on proliferation have been linked to Wnt1." (PMID 31979312, 2020). "By contrast, LRP5-deficient mice are viable, but develop Wnt1-induced mammary tumors much later than control mice, suggesting that LRP6 cannot compensate for LRP5 loss." (PMID 29854300, 2018). "Starting from the discovery of the oncogenic role of Wnt1 in murine MMTV-Wnt1 mammary tumors, a growing body of evidence has implicated Wnt/β-catenin signaling in human breast tumorigenesis." (PMID 27420097, 2016). "Wnt1-induced tumours appeared more than 36 weeks after the completion of pregnancy, again ruling out pregnancy-associated breast cancer as the cause of the cancer." (PMID 24381250, 2013). "Wnt1-induced mammary tumors frequently contain activating H-Ras mutations and mutations in K-Ras or N-Ras are frequently found in c-Myc-induced tumors." (PMID 19197353, 2009). "Using this approach we previously defined three Tumor-Associated Collagen Signatures (TACS) in mammary tumors from both Wnt-1 and PyVT transgenic mice." (PMID 18442412, 2008). "An important example, the Int-1 gene which is a common integration site for MMTV in mammary tumours, encodes the homologue of the Drosophila wingless gene and was subsequently named Wnt1 (wingless/Int) in recognition of this conserved function." (PMID 17895999, 2007). "Cyclin D1 appears to be critical in some pathways of mammary tumorigenesis, because cyclin D1-deficient mice are resistant to breast cancers induced by the c-neu and Ha-ras oncogene, but remain fully sensitive to breast cancers induced by c-myc and Wnt-1." (PMID 16536875, 2006).
breast cancer (continued). "Interestingly, nearly 70% of Wnt1-LateEx mammary tumors carried mutations in codon 61 of the Hras gene, which, in association with other PI3K/AKT pathway alterations, have also been recently identified as a main driver in the pathogenesis of AMEs in human." (PMID 40624726, 2025). "Interestingly, despite being the first Wnt gene associated with breast cancer tumorigenesis in mice, WNT1 is hardly found overexpressed in human breast cancers." (PMID 35663403, 2022). "In MMTV associated mouse mammary tumours, the oncogene Wnt-1 is highly expressed." (PMID 35458452, 2022). "Wnt3a and Wnt7a are likewise upregulated in metastatic breast cancer cell lines in association with poor prognosis and inhibition of Wnt/β-catenin signaling via Wnt1 knockdown could efficiently suppress cell proliferation and tumor growth." (PMID 33585487, 2021). "Interestingly, feeding HFD to female mouse mammary tumor virus-Wnt-1 transgenic (Tg) mice resulted in higher incidence of breast cancers in their offspring; this was associated with downregulation of Pten." (PMID 32582754, 2020). "In addition, we also found reduced tumor sphere formation in Wnt1-driven mammary tumor cells upon loss of FAK, as in PyMT-driven tumor cells we reported earlier." (PMID 32493400, 2020). "Using markers such as Wnt-1 may in future identify breast cancer patients with a high risk of tumor recurrence and/or progression to metastasis, who may then benefit from further intensive therapy after a surgery." (PMID 30558303, 2018). "Furthermore, loss of epithelial Pygo2 delayed mammary tumor onset in mouse mammary tumor virus (MMTV)-Wnt1 transgenic mice." (PMID 28055972, 2017). "In conclusion, TPA-induced migration of MCF-7 breast cancer cells is associated with the up-regulation of fascin-1 gene transcription, which is mediated through the activation of the PKCδ/STAT3α, PKCδ/GSK3β/β-catenin, and Wnt-1/β-catenin signaling pathways." (PMID 27036017, 2016). "For example, treatment of the transgenic mouse mammary tumor virus (MMTV)-Wnt1 breast cancer model with the RARα agonist Am580 inhibits the Wnt pathway and increases tumor-free survival." (PMID 41035698, 2025). "A shared feature of the TSG101 and late Wnt1-induced luminal-type mammary tumors is the expression of genes that belong to the basal gene cluster (left)." (PMID 40624726, 2025). "The computational analysis revealed that TSG101-overexpressing tumors are most similar to luminal-type mammary cancers that developed late in MMTV-Wnt1 (Wnt1-LateEx) transgenic females." (PMID 40624726, 2025). "The influence of DOXO on the different cells utilized in the present study can be seen in the view that although WNT1 proves the capacity of the WNT/β-catenin pathway to initiate breast cancer, the WNT1 protein is hardly overexpressed in human breast cancer." (PMID 40952540, 2025). "Studies on transgenic mouse models have demonstrated that inhibiting the expression of Wnt1 alleviates the growth and progression of breast cancer." (PMID 39071493, 2024). "In summary, our data showed that overexpression of Wnt1 induced osteoblastic change in an osteolytic breast cancer model." (PMID 37840014, 2023). "Kras or Hras is known to be spontaneously activated in precancerous mammary epithelial cells to instigate tumor formation in transgenic models of breast cancer, including in mice transgenic for Wnt1 under the control of mouse mammary tumor virus (MMTV) LTR." (PMID 37172086, 2023). "This small molecule inhibited growth in mouse models of breast cancer with Wnt1 overexpression by 52% and 78% at a daily dose of 1 and 3 mg/kg, respectively, without significant weight loss." (PMID 37047705, 2023).
breast cancer (continued). "The first link between WNT signaling and breast cancer was established when WNT1 was identified as a proto-oncogene capable of driving mammary tumor formation in mice." (PMID 38081857, 2023). "Wnt ligands (WNTs) were linked to cancer when the insertion of the mouse mammary tumor virus (MMTV) into the promoter of int1, the murine ortholog of wingless (later termed Wnt1), was discovered to induce mammary tumors in mouse models." (PMID 36982422, 2023). "Early evidence for the involvement of the Wnt pathway in cancer came from the isolation of Wnt-1, a gene activated by the integration of the mouse mammary tumor virus in a mammary tumor model." (PMID 37185433, 2023). "Wnt/β‐catenin signaling also contributes to mouse mammary cancer, initially found through the identification of Wnt1 as a mammary oncogene." (PMID 36106661, 2022). "It has been shown that Wnt-1 expression in breast cancer cells is significantly higher than in healthy cells, and breast cancer growth is enabled by their rapid proliferation." (PMID 35453754, 2022). "Overexpression of miR-148a restrains the development of breast cancer cells by regulating WNT-1, but miR-148a-3P has an adverse role." (PMID 36199758, 2022). "Grossly, the RSPO3/WNT1 mammary tumors showed a combination of compact solid areas as well as more dilated cystic areas typically seen in RSPO3‐ or WNT1‐driven mammary tumors, respectively." (PMID 36106661, 2022). "Wnt-1 expression is much higher in MMTV-like positive breast cancer specimens than in MMTV-like negative breast cancer specimens, which is consistent with studies showing high Wnt-1 expression in MMTV positive mouse mammary tumors." (PMID 35419411, 2022). "Given the reported interplay in the Wnt/β‐catenin pathway, we comparatively analyzed RSPO3‐driven mouse mammary tumors versus classical WNT1‐driven analogues." (PMID 36106661, 2022). "Co‐expression of Rspo3 and Wnt1 transduced mammary tumors with a mixed phenotype harboring morphological features characteristic of both transgenes." (PMID 36106661, 2022). "Altogether, in line with the different tumor morphologies of RSPO3‐ and WNT1‐driven mammary tumors, gene expression analysis revealed that their molecular profiles are also distinct." (PMID 36106661, 2022). "These morphological differences were further substantiated upon RNA sequencing analysis, which revealed that RSPO3‐ and WNT1‐driven mammary tumors have distinctive molecular profiles." (PMID 36106661, 2022). "Strikingly, we found that RSPO3‐driven mammary tumors appeared as completely different entities from those driven by WNT1." (PMID 36106661, 2022). "To look into this further, we assessed the gene expression profiles of RSPO3‐ versus WNT1‐driven mouse mammary tumors by RNA sequencing analysis of the respective mammary tumor tissues." (PMID 36106661, 2022). "WNT1‐driven mouse mammary tumors showed consistent and strong staining for both K8 and K5 in a bi‐layered fashion, clearly segregating luminal and basal cell layers and indicating a distinctive degree of differentiation." (PMID 36106661, 2022). "Since RSPOs are most often envisioned as agonists of the canonical Wnt pathway, we studied our RSPO3 breast cancer mouse model in parallel to the WNT1‐driven counterpart." (PMID 36106661, 2022). "The overexpression of miR-148a in breast cancer cell lines suppresses in vitro migration and invasion by directly targeting WNT-1 and inhibiting the activation of the Wnt/β-catenin pathway." (PMID 36012638, 2022). "FVB.Cg-Tg(Wnt1)1Hev/J female mice with activated wnt1 signaling develop spontaneous mammary tumors starting around 2-3 months of age and have been used as a mouse model for breast cancer research." (PMID 35756611, 2022). "In hepatocellular carcinoma, let-7a-5p directly targets Wnt1 to reduce the stemness of cancer cells; and in breast cancer, let-7c inhibits the Wnt/β-catenin signaling activation to induce the asymmetric division of CSC." (PMID 35287556, 2022).
breast cancer (continued). "We also identified the promoter hypermethylation of WNT1 in cfDNA as a potential noninvasive biomarker for luminal breast cancer." (PMID 36393855, 2022). "FVB.Cg-Tg(Wnt1)1Hev/J transgenic mice develop spontaneous mammary tumors starting around the age of 2-3 months and have been a widely-used mouse model for breast cancer research." (PMID 35756611, 2022). "RSPO3‐driven mouse mammary tumors are distinct from WNT1‐driven counterparts and uniquely present with poor differentiation, malignant transformation, and metastatic potential." (PMID 36106661, 2022). "In a MMTV-Wnt1 transgenic mouse model, Wnt1 secreted by luminal subtype of breast cancer cells promoted the proliferation of basal-like recipient cells." (PMID 36096830, 2022). "To obtain a comprehensive insight into the molecular routes that are differentially activated in RSPO3‐driven compared with WNT1‐driven mammary tumors, we performed gene ontology analysis." (PMID 36106661, 2022). "Encouragingly, inhibiting Wnt1 relieved the growth and progression of breast cancer in a transgenic murine model." (PMID 34456337, 2021). "Nonetheless, mammary tumors develop in ERKO/Wnt-1 mice more slowly than in mice that have ER-α, suggesting a role of ER-α in tumor promotion." (PMID 34361004, 2021). "Consistent with previous findings in breast cancer cells, we observed an enrichment of Six3 to the promoter regions of Wnt1 compared to the corresponding IgG control in AGS and HGC-27 cells." (PMID 34545072, 2021). "For example, LncRNA HOTTIP facilitates the development of breast cancer by regulating the miR-148a-3p/WNT1 pathway." (PMID 34193130, 2021). "Collectively, these findings suggest that dormant tumor cells that survive HER2/neu or Wnt1 downregulation exhibit gene expression profiles resembling those of normal mammary stem cells and tumorigenic breast cancer cells." (PMID 34088357, 2021). "The M1-like CD11c+ macrophages (MC2) were more abundant in pancreatic cancer models and in the Wnt1 breast cancer model." (PMID 33653826, 2021). "The development of estrogen-dependent mammary tumors in ERKO/Wnt-1 mice, even in the presence of an anti-estrogen, constitutes some of the strongest evidence for an ER-independent mechanism of cancer initiation by estrogens." (PMID 34361004, 2021). "Another developing theme on CD151 in breast cancer is its promoting role in development and growth of basal-like mammary tumors driven by the oncogenic Wnt1 pathway." (PMID 33919420, 2021). "The resulting double transgenic MMTV–Prune-1/Wnt1 mouse model (n = 31) developed mammary tumors (with 100% penetrance), as did the MMTV–Wnt1 mice (n = 44)." (PMID 33426510, 2021). "Namely, Ser81 phosphorylation by CK2 results in increased expression of STAT5A and WNT1 and thus plays a role in breast cancer cell biology also possibly affecting the process of inflammation related to breast cancer development and progression." (PMID 34638264, 2021). "Together, these results suggest that FAK regulation of mTOR signaling pathway contributes to its promotion of tumor growth and metastasis of Wnt1-driven and basal-like breast cancer." (PMID 32493400, 2020). "As in other models and consistent with a role for FAK in regulating cell migration in many cell types, we found reduced cell migration upon FAK deletion in Wnt1-driven mammary tumor cells." (PMID 32493400, 2020). "At 5 weeks after the initial detection of primary mammary tumors, histological analysis of lung sections showed metastatic nodules in about 28.5% (6 out of 21) of Ctrl-Wnt1 mice." (PMID 32493400, 2020). "This enables the activation of Cre-recombinase upon administration of 4-OHT, leading to deletion of FAK in isogenic Wnt1-driven mammary tumor cells." (PMID 32493400, 2020). "In fact, the first mammalian WNT gene (Wnt1, originally identified as int-1) was discovered as a proto-oncogene capable of driving mammary tumor formation in mice." (PMID 32083079, 2020).